CLOCK (clock circadian regulator)
Diseases named in the same sentence as CLOCK in open-access papers (continued):
Sharing a sentence is not in itself a finding about the gene and the disease.
cancer (109 papers, 2011 to 2026). A tumor composed of atypical neoplastic, often pleomorphic cells that invade other tissues. "Rev-erbα, a known circadian modulator playing a pivotal role in the cyclic Bmal1 and CLOCK transcription, has been implicated in a variety of physiological and pathophysiological processes, such as metabolism, cancers, and inflammatory responses." (PMID 35668454, 2022). "A similar phenomenon was also observed in cancer patients: CLOCK and the BMAL1 were closely associated with the extent of CD8+ T cell infiltration." (PMID 35326729, 2022). "The four integral clock proteins, PER, CRY, BMAL1, and CLOCK, all have complex molecular roles that can improve our understanding of cancer risk and biologically/clinically relevant outcomes." (PMID 35356228, 2022). "In agreement with this, we demonstrate that CLOCK is frequently mutated across cancers despite its minimal change in the mRNA level." (PMID 31708917, 2019). "Importantly, CLOCK-deficiency or OLZ alleviated chronic stress-enhanced chemoresistance to anti-cancer agent GEM." (PMID 39054537, 2024). "Other studies in non-cancer patients have reported an association between the C-allele in the SNP rs1801260 of CLOCK with eveningness that could contribute to a lower morning physical activity." (PMID 34979978, 2022). "Therefore, further studies are needed to comprehensively elucidate the geological roles of CLOCK polymorphisms in the development and progression of different types of cancer." (PMID 30843665, 2019). "As for CLOCK the effect could be attributed to a different susceptibility depending on the cancer type." (PMID 30518396, 2018). "Moreover, previous studies have indicated that the depletion of T cells and up-regulation of programmed death-ligand (PD-1) in patients with cancer may be associated with the widespread mutation and genomic instability of the CLOCK gene." (PMID 36647780, 2023). "However, previous research among non-cancer patients could correlate the C-allele in the SNP rs1801260 of CLOCK with eveningness, leading to lower morning physical activity." (PMID 34979978, 2022). "However, future study is needed to elucidate the mechanisms underlying the effect of PFKFB3 inhibition on reducing CLOCK expression, and to determine the extent to which other CLOCK-associated mechanisms contribute to the anti-cancer effect of 3PO in a timed manner." (PMID 27079271, 2016). "However, the identification of differential correlation structure provides the first integrated hypothesis that suggests MAX could modulate the co-expression of ATF4 and CLOCK, leading to differential cancer drug susceptibility." (PMID 26539209, 2015). "Clinically, poor sleep quality and low serum β-endorphin correlate with tumor progression and elevated CLOCK/ACSL1 expression, suggesting β-endorphin as a potential therapeutic for SD-associated cancers." (PMID 40977744, 2025). "Sleep-deficiency-dysregulated CLOCK hypertransactivates ACSL1 to stimulate fatty acid oxidation, mitochondrial respiration, and ATP production, thereby promoting cancer progression." (PMID 40740866, 2025). "This forms a positive feedback loop that stabilizes CLOCK, preventing its degradation and perpetuating circadian disruption while maintaining SD-enhanced cancer stemness." (PMID 40977744, 2025). "This metabolite promotes the S‐palmitoylation of CLOCK at Cys194, establishing a feedback loop that protects CLOCK from ubiquitin‐proteasomal degradation, thereby maintaining cancer stemness despite circadian disruptions." (PMID 39726221, 2025). "In cancer cells, CLOCK gene disruption induces NAD+ imbalance through consumption outpacing production, which sustains biosynthetic requirements while driving NAD+ depletion‐mediated aerobic glycolysis and tumor proliferation." (PMID 40772466, 2025).
cancer (continued). "Mutations and copy number variations in circadian clock genes, such as ARNTL2 in colorectal cancer and NPAS2, CLOCK, and PER3 in breast cancer, are linked to cancer progression, suggesting their potential as biomarkers for cancer risk and prognosis." (PMID 39566400, 2024). "Even so, increased cancer susceptibility is also located in clock genes rs117104877, rs2290035, rs2278749, and rs969485 in BMAL1 and rs3749474 and rs11943456 in CLOCK." (PMID 38892035, 2024). "NE activated ADRB2-cAMP-PKA-CREB pathway to promote CLOCK transcription, leading to cancer stem-like traits." (PMID 39054537, 2024). "As such, OLZ downregulated CLOCK expression to reverse chronic stress-enhanced chemoresistance to first-line anti-cancer agent GEM." (PMID 39054537, 2024). "For instance, CLOCK was selectively expressed in ER+ cancer, whereas PER1 and TEF were highly expressed in both ER+ and HER+, and finally PER3 was expressed in HER2+ and TNBC." (PMID 39201344, 2024). "Taken together, our finding indicates that circadian gene CLOCK mediated NE-induced tumor growth and cancer stemness." (PMID 39054537, 2024). "More lately, our lab and others have shown that the master circadian E-box-binding regulators, BMAL1 and CLOCK, also have important functions in several cancer types." (PMID 37601651, 2023). "PER2 was found to be highly associated with activation of PI3K/AKT oncogenic pathway and cancer metabolism, while CLOCK was quite the opposite." (PMID 37183243, 2023). "Discovering BMAL1 and CLOCK, the forementioned master transcription factors of circadian rhythms, are required for cancer cell proliferation has encouraged experimental and clinical investigations to inform novel anticancer strategies." (PMID 36937362, 2023). "Genetic studies demonstrated that transcriptional regulation of WEE1 and p21 cooperatively contributes to cancer cell proliferation promoted by BMAL1::CLOCK." (PMID 36937362, 2023). "Collectively, our observations support the concept that anti-apoptosis activity of the cancer-specific WEE1 contributes to BMAL1::CLOCK stimulated HCC cell proliferation." (PMID 36595671, 2023). "Meanwhile, BMAL1/CLOCK knockdown induces the downregulation of the WEE1 gene, which encodes a checkpoint kinase essential for cancer cells’ survival and, consequently, leads to enhanced genome instability and apoptosis." (PMID 36937362, 2023). "The CLOCK gene enhances VEGF-mediated angiogenesis in cancer cells and metastatic invasion by interacting with HIF-1α/BMAL1." (PMID 36672355, 2023). "On the other hand, in some cancers, BMAL1 or CLOCK act as oncogenes, but in other cancers and model systems, their targeting is tumor suppressive." (PMID 36895015, 2023). "In cancer, several CC genes, including CLOCK, ARNTL, PER2 and NR1D1 are dysregulated and play a role in tumourigenesis." (PMID 35884519, 2022). "In some tissues, the CLOCK gene can be designated to promote cancer, acting as an oncogene, whereas in others, it acts as a tumor inhibitor." (PMID 36556190, 2022). "It has been demonstrated that knockdown of either BMAL1 or CLOCK has been observed to induce cell cycle arrest and apoptosis in cancer stem cells in a patient-derived glioblastoma cell or murine leukemia stem cells in acute myeloid leukemia." (PMID 35984550, 2022). "Discrepancies in the expression of the CLOCK gene in cancer provokes alterations in the activation and/or inhibition of the main oncogenic and tumor suppressive pathways." (PMID 36556190, 2022). "GEPIA was used to understand the messenger (m)RNA expressions of circadian rhythm-related factors in the PER family (PER1, PER2, and PER3), CRY family (CRY1 and CRY2), BMAL1, and CLOCK in different types of cancer." (PMID 36385012, 2022). "The UALCAN database showed expressions of circadian factors, including PER and CRY family members, BMAL1 (ARNTL), and CLOCK, with differential expression levels between different types of cancers and normal tissues." (PMID 36385012, 2022).
cancer (continued). "TGFβ1-induced invasion of cancer cells into collagen type 1 was assessed using a 3D cell culture chip, and the invasive potential of enhanced CLOCK-expressing 4T1 cells was lower than that of Mock-transduced 4T1 cells (p<0.01)." (PMID 33890571, 2021). "Compared with the adjacent normal tissues, the expression of NR1D1, DBP, and BHLHE40 was increased, while the expression of CRY1 and CLOCK was decreased in cancer tissues." (PMID 34977153, 2021). "In support of the pro-tumor role of the CLOCK gene, other evidence found that CLOCK knocking-down decreased cancer proliferation, progression and invasion as well as expression of several cancer-associated genes." (PMID 33114365, 2020). "Overexpression of CLOCK protein in cisplatin-resistant cancer cells was confirmed in the similar study that also revealed a significant correlation between CLOCK expression and cisplatin sensitivity." (PMID 33114496, 2020). "Circadian positive feedback loop (CPFL) genes (CLOCK, BAML1, and NPAS2) have been implicated in cancer initiation and progression." (PMID 30843665, 2019). "This circadian-cancer link was confirmed in a meta-analysis showing association between risk of cancer and variants in NPAS2, RORA, RORB, and CLOCK." (PMID 31303884, 2019). "Studies on the relationship between clock genes polymorphisms and cancer susceptibility have established that variants of ARNTL, CLOCK, CK1ε, CRY1-2, NPAS2, and PER1-3 are frequently associated to human reproductive tissues and pancreatic cancers." (PMID 30873119, 2019). "The link identified in our research between BMAL1, CLOCK, and Rho GTPase activity presents an innovative therapeutic targeting strategy of Rho GTPase in cancer." (PMID 30287810, 2018). "The genes that contributed the most to the overall association with cancer risk were NPAS2, CLOCK and RORs (RORA and RORB)." (PMID 28177907, 2017). "This clock–cancer link was confirmed in later studies which showed genetic associations between some variants of the clock genes NPAS2, CRY2 and CLOCK and the risk of breast carcinoma, prostate carcinoma and Non-Hodgkin lymphoma." (PMID 28177907, 2017). "In our research, mRNA expression of NPAS2 was robustly decreased after PER1 knockdown, indicating that the compensatory effect on CLOCK/BMAL1 was weakened due to PER1 knockdown in cancer cells." (PMID 27602964, 2016). "This process prevents the degradation of CLOCK protein via the ubiquitin–proteasome pathway, thereby sustaining the enhanced stemness of cancer cells induced by circadian rhythm disruption, and continuously driving cancer development." (PMID 40046513, 2025). "Additionally, it has been demonstrated that the core BMAL1::CLOCK transcription apparatus is crucial for maintaining stemness in at least two distinct cancer types." (PMID 38892035, 2024). "Here, our results provide molecular insights into this HCC-clock crosstalk by unveiling that the core clock transcription factor BMAL1::CLOCK is hijacked by cancer cells to fuel rapid cell proliferation and inhibit apoptosis in HCC, independent of the genetic background or core clock oscillations." (PMID 36595671, 2023). "Here, we briefly discuss the roles of CLOCK/BMAL1 in in several representative cancers." (PMID 36647780, 2023). "Therefore, focusing on these immune responses associated with CLOCK and BMAL1 should provide new insights into cancer treatment." (PMID 36647780, 2023). "Interestingly, down-regulation of PER1-3, CRY2, NPAS2, BMAL1, as well as CLOCK gene expression, correlates with high histological grade and poor prognosis and short survival in different cancers." (PMID 36672355, 2023). "We described some potential mechanisms through which CLOCK affects cancer progression." (PMID 36647780, 2023). "Part of the reason is that mutations in BMAL1 and CLOCK are not commonly observed in cancer, implying that they themselves do not commonly function as mutated drivers of tumor initiation." (PMID 37601651, 2023).
cancer (continued). "Furthermore, BMAL1 and CLOCK interact with cyclin B1 to control cell cycle G2/M checkpoint, a vital regulatory step dysregulated in cancer." (PMID 36635730, 2023). "Recent studies have discovered pivotal roles for BMAL1 and CLOCK in multiple types of cancers." (PMID 37601651, 2023). "Because of the low expression of BMAL1 and CLOCK in the results found, it is possible that this deregulated mechanism aids in the continuous cell proliferation of leukemic cells, as it has been shown in other types of cancer." (PMID 35897788, 2022). "This suggests that at the molecular level, CLOCK-regulated miRNAs may be involved in cancer initiation or progression by directly controlling cell proliferation, cell invasion, or metabolism-related genes in the mouse liver." (PMID 31799078, 2019). "Notably, the effects of BMAL1 and CLOCK overexpression in this assay were both mild, potentially due to the intrinsically high endogenous expression of BMAL1 and CLOCK in cancer cells." (PMID 30287810, 2018). "In addition, the expression of key clock genes whose products generate feedback inhibitory effects on BMAL1/CLOCK transcription activity in cancer tissues and its surrounding tissues was distinct from that in normal tissues." (PMID 27079271, 2016). "In contrast, the expression of CLOCK and CKIɛ was significantly higher in cancer tissue." (PMID 27492458, 2016). "Our previous studies identified CLOCK/BMAL1 transcriptional activity as a target for pharmacological intervention to, among other potential applications, reduce the toxicity associated with genotoxic anti-cancer treatments." (PMID 22249125, 2011). "Furthermore, CLOCK and CRY1 might possess tumorigenic characteristics, and this is substantiated by whole-genome expression microarray studies that found expression of multiple cancer-related transcripts to be modified after CLOCK gene knockdown." (PMID 39587706, 2024). "This evidence suggests that CLOCK gene expression in cancer cells may contribute to immune escape." (PMID 36647780, 2023). "Simultaneously, BMAL1/CLOCK also activates the transcription of numerous downstream clock-controlled genes by adhering to the E-box, thus regulating a number of physiological functions, such as energy metabolism, reproductive capacity, cell apoptosis, cancer, and immunoendocrine signals." (PMID 35478603, 2022). "Through this HAT activity, CLOCK may play a pivotal role in chromatin remodeling and in modulating the activity and the transcription of proteins involved in cell cycle control and DNA damage response, thereby influencing cancer development." (PMID 33114365, 2020). "Those authors suggest that CLOCK, together with ER, could promote cancer cell proliferation." (PMID 29958276, 2018). "As the synergistic effect of CLOCK and ATF4 has been implicated in multidrug resistance through glutathione-dependent redox system, a breakdown in this correlation could lead to differential drug response in human cancer." (PMID 26539209, 2015). "This study uncovers a promising therapeutic strategy for a broader subset of patients with GBM with high expression of either CLOCK or TFPI2, and provides a framework for identifying 'symbiotic exclusivity' genes in cancer." (PMID 41842961, 2026). "The dynamic interplay between CLOCK and ASS1 not only highlights the importance of temporal control in cellular metabolism but also reveals potential therapeutic targets for cancer and vascular disorders." (PMID 41295280, 2025). "The E-box regulators BMAL1, CLOCK, CRY1, and PER1, as proteins, play a role in several cancers, and MB should be added to the list of those cancers." (PMID 40002179, 2025). "There is growing recognition that the roles of CLOCK and BMAL1 in the development of cancer vary significantly depending on the context and type of disease." (PMID 39001398, 2024).
cancer (continued). "Circadian rhythms are controlled by a set of regulatory molecules like the protein CLOCK (circadian locomotor output cycles kaput), brain and muscle ARNT-like protein 1 (Bmal1), PER1 and PER2, all of which seems to be dysregulated in cancer." (PMID 39199335, 2024). "Although associations have been identified between IL-4, IL-6, IL-8, IL-10, IL-1β, TNF-α, COMT, CLOCK, PER, and 5-HTTLPR-related genes and cancer-related fatigue, the relationship between IL-6 and cancer-related fatigue remains controversial." (PMID 39372868, 2024). "This interaction holds significant clinical relevance because the expression of clock genes and their proteins, such as CLOCK and BMAL1, has been shown in certain cancers, including leukemia, to acetylate glucocorticoid receptors." (PMID 39518143, 2024). "Regarding prostate cancer (PCan), various clock genes, such as ARNTL, CLOCK, BMAL1, Ck1ε, CRY1, CRY2, Npas2, and PER1-3, are found to be involved in this type of carcinoma." (PMID 38892035, 2024). "Recently it has been reported that curcumin targets different molecules regulating the circadian timing system with anti-cancer activity such as PER2, BMAL1, and CLOCK." (PMID 36796229, 2023). "The results revealed significant downregulation of CLOCK, PER1, PER2, PER3, CRY1, CRY2, REV-ERBα, and RORα in cancer tissues compared with matched normal tissues." (PMID 37240325, 2023). "The relationship between circadian genes—including ARNTL, CLOCK, and PER1/2/3—and the onset of cancer has been thoroughly studied over the past few decades." (PMID 38053143, 2023). "CLOCK genes such as BMAL1 and REV-ERB mainly play an anticancer role while DEC has both anticancer and cancer-promoting effects in relevant literature." (PMID 38189049, 2023). "Across different cancers, we observed that the negative regulatory genes are downregulated while the positive regulatory genes, such as BMAL1 and CLOCK, show minimal alterations." (PMID 31708917, 2019). "The alteration frequencies of core clock genes were lower than 5% in most cancers, with the exception of PER3 in CHOL and CLOCK in LUSC." (PMID 30791227, 2019). "In numerous cancers, the dysfunction of the canonical WNT pathway is accompanied by alterations of the circadian genes (CLOCK, BMAL1, PER)." (PMID 31803621, 2019). "For instance, PER1 was deleted in 16 cancers, while PER3 and CLOCK were lost in 15 and 12 cancers respectively." (PMID 31014368, 2019). "An oncogenic-driven mouse model identified CLOCK and BMAL1 as playing a key role in regulating proliferation and differentiation pointing to a complex role of the circadian clock in cancer progression." (PMID 29216180, 2017). "Compared with those in normal epithelium, the mRNA levels of PFKFB3 were increased in both cancer tissues and its surrounding tissues, which were accompanied with significant decreases in the mRNA levels of BMAL1 and CLOCK in the same tissues." (PMID 27079271, 2016). "Mice that are not naturally prone to cancer exhibit premature aging after introducing artificial mutations in BMAL1 and CLOCK genes." (PMID 39812541, 2025). "Yet, the mechanism by which NE regulates CLOCK rather than other core circadian genes to promote cancer stemness remains unexplored." (PMID 39054537, 2024). "Examples include CLK8, which disrupts BMAL1/CLOCK interactions, and compounds like a derivative of 2-ethoxypropanoic acid and ARN5187, which target CRY1/2 and REV-ERBβ proteins, showing promise for treating circadian disorders and cancer." (PMID 39566400, 2024). "Therefore, melatonin is the one that enhances PER2 and CLOCK and decreases BMAL1 in this type of carcinoma." (PMID 38892035, 2024). "Additionally, CLOCK and BMAL1 overexpression can promote cancer cells growth by affecting F-actin formation, indicating that regulation of BMAL1 has diverse effects on tumor proliferation, invasion and metastasis across different oncogenic pathways." (PMID 38189049, 2023).